COL8A1 (collagen type VIII alpha 1 chain)
Description:
Macromolecular component of the subendothelium. Major component of the Descemet's membrane (basement membrane) of corneal endothelial cells. Also a component of the endothelia of blood vessels. Necessary for migration and proliferation of vascular smooth muscle cells and thus, has a potential role in the maintenance of vessel wall integrity and structure, in particular in atherogenesis. Vastatin, the C-terminal fragment comprising the NC1 domain, inhibits aortic endothelial cell proliferation and causes cell apoptosis.
Synonyms: C3orf7; MGC9568
Tractability: Antibody: its Gene Ontology location is reachable by antibodies, with high confidence; UniProt places it where antibodies can reach, with medium confidence; UniProt predicts a signal peptide or a membrane-spanning region.
Gene: Protein-coding gene on chromosome 3 (99,638,426 to 99,799,226, forward strand). Ensembl gene ENSG00000144810.
Subcellular location: Secreted, extracellular space, extracellular matrix, basement membrane
Subcellular location (Human Protein Atlas): Vesicles; Predicted to be secreted
Pathways (Reactome):
Extracellular matrix organization: Assembly of collagen fibrils and other multimeric structures; Collagen biosynthesis and modifying enzymes; Collagen chain trimerization; Collagen degradation; Integrin cell surface interactions
Gene Ontology:
Molecular function: protein binding; extracellular matrix structural constituent conferring tensile strength
Biological process: endodermal cell differentiation; basement membrane assembly; extracellular matrix organization
Cellular component: extracellular matrix; collagen type VIII trimer; elastic fiber; endoplasmic reticulum lumen; extracellular region; basement membrane
Genetic constraint (gnomAD): Loss-of-function variants: 21 observed, 44.2 expected, observed/expected ratio (o/e) 0.48, 90% interval 0.34 to 0.68. The upper end of that interval is the gene's LOEUF score, 0.68, which puts it in group 2 of 6, group 1 being the genes least tolerant of losing a copy. Missense variants: 787 observed, 991.92 expected, observed/expected ratio (o/e) 0.79, 90% interval 0.75 to 0.84. Synonymous variants: 367 observed, 377.05 expected, observed/expected ratio (o/e) 0.97, 90% interval 0.89 to 1.06.
Homologues: Orthologues: chimpanzee COL8A1 (99% identical), macaque COL8A1 (99% identical), guinea pig COL8A1 (96% identical), rabbit COL8A1 (95% identical), pig COL8A1 (95% identical), dog COL8A1 (94% identical), rat Col8a1 (94% identical), mouse Col8a1 (93% identical), tropical clawed frog col8a1 (66% identical), zebrafish col8a1b (64% identical). Paralogues in human: COL8A2 (50% identical), COL10A1 (47% identical), COL19A1 (37% identical), OTOL1 (22% identical), C1QTNF9 (17% identical), C1QTNF9B (17% identical), C1QTNF2 (13% identical), C1QTNF7 (13% identical), C1QC (12% identical), ADIPOQ (12% identical), C1QTNF3 (12% identical), C1QB (12% identical), and 11 more.
Diseases named in the same sentence as COL8A1 in open-access papers:
COL8A1 is named in the same sentence as 93 diseases in open-access papers, as found by Europe PMC text mining. Sharing a sentence is not in itself a finding about the gene and the disease. The quoted sentences say what the papers report.
gastric cancer (12 papers, 2019 to 2025). A primary or metastatic malignant neoplasm involving the stomach. "The strong association of COL8A1 with various aspects of gastric cancer pathogenesis reinforces its potential as a therapeutic target." (PMID 40461943, 2025). "Recently, some studies demonstrated that upregulation of COL8A1 is associated with poor survival in gastric cancer, renal cell carcinoma, and breast cancer." (PMID 37188982, 2023). "Elevated COL8A1 expression was found in gastric cancer patients and higher COL8A1 correlated with advanced tumor stages and worse overall survival condition; and COL8A1 was selected as a candidate diagnostic biomarker in gastric cancer." (PMID 32818022, 2020). "This in vivo evidence corroborates our in vitro results and underscores the potential of COL8A1 as a therapeutic target for inhibiting gastric cancer progression." (PMID 40461943, 2025). "Our in vitro experiments demonstrated that COL8A1 promotes the proliferation and invasion of human gastric cancer cell lines." (PMID 41004487, 2025). "Given the critical role of ECM remodeling in shaping the tumor microenvironment, promoting tumor invasion, and driving chemoresistance in gastric cancer, COL8A1 emerges as an intriguing therapeutic target worthy of further investigation." (PMID 41004487, 2025). "Further investigation of COL8A1 revealed its significant role in gastric cancer cell proliferation, metastasis, and chemoresistance." (PMID 40461943, 2025). "Given the critical role of the PI3K/AKT pathway and EMT in gastric cancer, targeting COL8A1 in STAD patients is theoretically justified." (PMID 41004487, 2025). "The results revealed a significant up‐regulation of COL8A1 expression in recurrent gastric cancer tissues compared to non‐recurrent cases." (PMID 40461943, 2025). "However, studies investigating COL8A1 in gastric cancer remain limited, particularly regarding its role in recurrence and treatment resistance." (PMID 40461943, 2025). "In gastric cancer, upregulation of COL8A1 promotes cell proliferation and indicates poor prognosis." (PMID 41004487, 2025). "Experiments on gastric cancer cells show that the silence of COL8A1 can obviously inhibit cell proliferation, migration, and invasion in GC." (PMID 35774273, 2022). "Based on the results of this bioinformatics analysis, we used our own clinically collected gastric cancer samples for immunohistochemical verification to explore the expression of COL8A1 in GC patients and its relationship with the EMT." (PMID 35774273, 2022). "The Cox proportional hazard model of COL8A1, COL10A1, CTHRC1, and FAP and six tumor-infiltrating immune cells in gastric cancer (TIMER)." (PMID 35910202, 2022). "However, the role of COL8A1 in gastric cancer remains unclear." (PMID 35774273, 2022). "NOX4 (logFC = 1.948, P = 4.55e-12), COL8A1 (logFC = 1.982, P = 1.22e-8) and CHST1 (logFC = 1.783, P = 9.04e-13) were significantly upregulated in gastric cancer tissues." (PMID 33193668, 2020). "Several studies have focused on the prognostic values of CAF-related genes in other cancers, a 4-CAF-gene (COL8A1, SPOCK1, AEBP1 and TIMP2) prognostic signature was developed to predict the clinical outcomes and the response to anti-tumor therapies in gastric cancer." (PMID 35873482, 2022). "-Analysis Type: Gastric Cancer vs. Normal Analysis-COL8A1; Analysis Type: Gastric Cancer vs. Normal Analysis-FRMD6; Analysis Type: Gastric Cancer vs. Normal Analysis-TIMP2; Analysis Type: Gastric Cancer vs. Normal Analysis-CNRIP1; Analysis Type: Gastric Cancer vs. Normal Analysis-GPR124." (PMID 32095347, 2020). "In the cohort from the GEPIA database, the expression of NOX4, COL8A1, and CHST1 in gastric cancer tissues was higher than that in normal tissues, and the expression levels of NOX4 (F = 5.67 and P = 0.0008) and COL8A1 (F = 6.49 and P = 0.0003) differed across the four pathological stages." (PMID 33193668, 2020).
gastric cancer (continued). "In addition, the expression of the target genes NOX4, COL8A1 and CHST1 in the brown module was upregulated in gastric cancer, and these genes could predict the prognosis of gastric cancer patients, as verified in 3 independent cohorts." (PMID 33193668, 2020).
breast carcinoma (10 papers, 2018 to 2025). "Tnc, Col8a1, Loxl3 and Plau), several of which have been shown to support cancer cell invasion and associate with poor clinical outcome in breast cancer patients." (PMID 38849373, 2024). "Furthermore, our study sheds light on the biological function and potential molecular mechanisms of COL8A1 underlying breast cancer." (PMID 32818022, 2020). "Alterations and mutations of COL8A1 in breast cancer were relatively frequent." (PMID 32818022, 2020). "Though the expression of COL8A1 in tissue cannot reflect the early diagnostic value in breast cancer, we assume that if COL8A1 is also differentially expressed in the bodily fluid of patients, it will be possible to serve as a potential diagnostic marker for breast cancer." (PMID 32818022, 2020). "Moreover, we explored the molecular mechanisms of COL8A1 underlying breast cancer to improve our knowledge of breast cancer carcinogenesis and progression." (PMID 32818022, 2020). "Furthermore, based on differentially expressed genes (DEGs) and co-expressed genes (CEGs) positively related to COL8A1, functional enrichment analyses were performed to explore the biological function and potential molecular mechanisms of COL8A1 underlying breast cancer." (PMID 32818022, 2020). "Studies have reported overexpression of COL8A1 in both lung and breast cancer, suggesting a potential role in tumorigenesis and disease progression." (PMID 40224214, 2025). "It is possible that COL8A1 participates in the communication of breast cancer cells and microenvironments." (PMID 32818022, 2020). "We also aimed to determine prognostic value of COL8A1 in breast cancer to pave the way for future clinical applications." (PMID 32818022, 2020). "Elevated COL8A1 expression correlated with race (white > black), molecular subtypes of breast cancer (luminal B > luminal A > TNBC), ER, PR, and HER-2 status." (PMID 32818022, 2020). "First, COL8A1 products belong to extracellular matrix protein and serve as one of the nineteen human collagens, which are important components of the breast cancer stroma." (PMID 32818022, 2020). "A DOR of 6.38 (95% CI 4.52–9.02) also highlighted the discriminatory ability of COL8A1 in breast cancer." (PMID 32818022, 2020). "Our diagnostic test showed a moderate discriminatory capability of COL8A1 between breast cancer and normal breast tissue." (PMID 32818022, 2020). "We were focused on investigating the expression of COL8A1 messenger RNA (mRNA) in various molecular subtypes of breast cancer by analyzing gene microarray and RNA sequencing data sets." (PMID 32818022, 2020). "We thus concluded that COL8A1 expression is higher in breast cancer patients than in control samples and that upregulation is independent of molecular subtypes of breast cancer." (PMID 32818022, 2020). "Immunohistochemistry staining showed varying coloration intensity of COL8A1 in breast cancer and normal breast tissue." (PMID 32818022, 2020). "This is the first study to investigate the protein expression of COL8A1 in breast cancer using immunohistochemistry staining." (PMID 32818022, 2020). "Thirteen of the twenty platforms showed much higher COL8A1 expression in breast cancer patients than in control samples." (PMID 32818022, 2020). "COL8A1 was negatively, weakly, moderately, or strongly stained in normal breast epithelium and breast cancer tissue." (PMID 32818022, 2020). "The highlight of this study is that it comprehensively explored the upregulation of COL8A1 mRNA in breast cancer from multiple aspects based on 5048 breast cancer patients and 1161 controls." (PMID 32818022, 2020). "We found higher COL8A1 expression in breast cancer than normal breast tissue based on 20 large platform matrices integrated from 53 data sets." (PMID 32818022, 2020). "COL8A1 was one of the key genes restored by epigallocatechin-3-gallate in a murine breast cancer model." (PMID 32818022, 2020).
breast carcinoma (continued). "Fourth, the expression levels of COL8A1 in the bodily fluid of breast cancer patients need to be explored." (PMID 32818022, 2020). "In-house immunohistochemistry staining was used to evaluate the protein expression of COL8A1 in breast cancer." (PMID 32818022, 2020). "More importantly, our study provides important clues about the role of COL8A1 in breast cancer for the first time." (PMID 32818022, 2020). "COL8A1 expression was higher in breast cancer patients than in control samples (standardized mean difference = 0.79; 95% confidence interval [CI] 0.55–1.03)." (PMID 32818022, 2020). "Nevertheless, no previous studies have demonstrated the expression level of COL8A1 in the bodily fluid of breast cancer patients until now." (PMID 32818022, 2020). "Second, the prognostic value of COL8A1 in breast cancer needs to be confirmed by large-scale clinical practice." (PMID 32818022, 2020). "An SMD value of 0.79 (95% confidence interval [CI]: 0.55–1.03) showed that COL8A1 expression was significantly higher in breast cancer than in non-breast cancer tissue." (PMID 32818022, 2020). "A Chi square test confirmed the significantly higher expression of COL8A1 in breast cancer than normal breast tissue (χ2= 8.428, P = 0.004)." (PMID 32818022, 2020). "Compared with other hundreds of markers already investigated in breast cancer, COL8A1 possessed several advantages." (PMID 32818022, 2020). "COL8A1 may promote breast cancer migration by affecting ECM receptor interactions and cooperation with other genes." (PMID 35774273, 2022). "COL8A1 was generally upregulated in breast cancer compared to normal breast tissue." (PMID 32818022, 2020). "Immunohistochemistry staining confirmed the upregulation of COL8A1 protein in breast cancer." (PMID 32818022, 2020). "Moreover, this study is the first to assess the clinical prognostic value of COL8A1 in breast cancer." (PMID 32818022, 2020). "COL8A1 mRNA expression in breast cancer was compared between molecular subtypes." (PMID 32818022, 2020). "Based on cBioPortal, COL8A1 was altered in 7% of 1108 breast cancer patients." (PMID 32818022, 2020). "Protein expression confirmed the upregulation of COL8A1 in breast cancer." (PMID 32818022, 2020). "Considering this knowledge gap, our study aimed to explore the role of COL8A1 in breast cancer." (PMID 32818022, 2020). "The clinical value of COL8A1 in breast cancer was found to be promising." (PMID 32818022, 2020). "Higher COL8A1 expression levels in breast cancer patients correlated with worse survival outcomes." (PMID 32818022, 2020). "We determined the clinical value of COL8A1 in breast cancer for the first time." (PMID 32818022, 2020). "Subsequently, we compared COL8A1 expression levels between different subtypes of breast cancer." (PMID 32818022, 2020). "Third, the precise molecular mechanisms of COL8A1 in breast cancer require further examination." (PMID 32818022, 2020). "This study demonstrates the upregulation of COL8A1 in breast cancer." (PMID 32818022, 2020). "First, the discriminatory capacity of COL8A1 in breast cancer is moderate." (PMID 32818022, 2020). "According to the staining intensity and color range percentages, 45.2% of breast cancer tissue specimens exhibited low and 54.8% exhibited high COL8A1 expression, whereas 67.7% of normal breast tissue specimens exhibited low and 32.3% exhibited high COL8A1 expression." (PMID 32818022, 2020). "Elevated COL8A1 may promote the migration of breast cancer by mediating the ECM-receptor interaction and synergistically interplaying with DEGs and its positively related CEGs independently of molecular subtypes." (PMID 32818022, 2020). "An area under a summary receiver operating characteristic curve of 0.80 (95% CI 0.76–0.83) with sensitivity of 0.77 (95% CI 0.69–0.83) and specificity of 0.70 (95% CI 0.61–0.78) showed moderate capacity of COL8A1 in distinguishing breast cancer patients from control samples." (PMID 32818022, 2020).
breast carcinoma (continued). "Therefore, the biological function of COL8A1 makes it distinctive from other markers of breast cancer." (PMID 32818022, 2020). "This study shows that COL8A1 upregulation may promote the migration of breast cancer by mediating ECM-receptor interaction and synergistically interplaying with DEGs and its positively related CEGs independently of molecular subtypes." (PMID 32818022, 2020). "Among the identified transcripts, downregulation of COL6A2, SERPINA1, CCBE1, TFPI2, THBS1 and COL8A1 have been shown to promote migration and invasion of malign breast cancer cells, aggravate metastatic spread and result in poor prognosis of breast cancer patients." (PMID 31848385, 2019). "Thus far, only few studies mentioned COL8A1 in breast cancer." (PMID 32818022, 2020). "Among the thirteen platforms showing high COL8A1 expression, twelve platforms indicated the ability of COL8A1 in differentiating breast cancer patients and control samples, where four platforms showed strong discriminatory capability of COL8A1 between breast cancer patients and control samples." (PMID 32818022, 2020). "Furthermore, high COL8A1 protein levels were related to ER- breast cancer." (PMID 32818022, 2020). "Thus, COL8A1 might serve as a prognostic marker for breast cancer." (PMID 32818022, 2020). "However, the role of COL8A1 in breast cancer remains unknown." (PMID 32818022, 2020). "Importantly, increases in COL8A1, BGN, COL11A1, POSTN, MMP11 and SORCS2 and decreased LTBP4, PCOLCE2, LRRC17 and SDK1 have been identified in CAS and CAFs from human breast cancer and are consistently perturbed in stroma of canine and human mammary cancer." (PMID 37391533, 2023). "As an important component of the ECM, COL8A1 itself may interfere with signaling from the ECM to cells, affect the formation of the ECM, and promote the migration of breast cancer by synergistically interplaying with DEGs and its positively related CEGs." (PMID 32818022, 2020). "Although collagen type VIII alpha 1 chain (COL8A1) has been shown to be downregulated in BRIP1-knockdown breast cancer cells, its clinical role in breast cancer remains unknown." (PMID 32818022, 2020). "Subgroup analysis based on four molecular subtypes of breast cancer showed that elevated COL8A1 expression is independent of subtypes." (PMID 32818022, 2020). "COL8A1 proved downregulated in both BRIP1-knockdown breast cancer cells and MCF10A CDH1-/- non-cancer breast cells." (PMID 32818022, 2020). "Moreover, elevated COL8A1 expression correlated with estrogen-negative (ER-) breast cancer (P = 0.018)." (PMID 32818022, 2020).
age-related macular degeneration (6 papers, 2016 to 2024). Age-related loss of vision in the central portion of the retina (macula), secondary to retinal degeneration. "Furthermore, COL8a1 and COL10a1 are associated with age-related macular degeneration whereas mutations in COL8a2 can lead to Fuchs endothelial dystrophy, an impairment of vision." (PMID 38997817, 2024). "On this subject, COL8A1 has been extensively investigated in other multifactorial disease, especially in Age-Related Macular Degeneration (AMD)." (PMID 31275967, 2019).
hepatocellular carcinoma (6 papers, 2020 to 2026). A malignant tumor that arises from hepatocytes. "The intersected CEGs positively related to COL8A1 and upregulated DEGs were significantly aggregated in several cancer pathways (such as thyroid cancer, colorectal cancer, and hepatocellular carcinoma)." (PMID 32818022, 2020). "Silencing of COL8A1 significantly inhibited the proliferation and invasion of hepatocellular carcinoma cell lines and increased the sensitivity to D-limonene in the treatment of hepatocellular carcinoma." (PMID 35774273, 2022). "Moreover, elevated COL8A1 in hepatocellular carcinoma promoted tumor cells proliferation, invasion, and in vivo tumorigenicity." (PMID 32818022, 2020). "Regarding the 1779 overlapping upregulated DEGs and CEGs positively related to COL8A1, the following KEGG pathways were significantly aggregated: proteoglycans in cancer, ECM-receptor interaction, and several cancer pathways (such as thyroid cancer, colorectal cancer, and hepatocellular carcinoma)." (PMID 32818022, 2020).